IL5 (interleukin 5)
Diseases named in the same sentence as IL5 in open-access papers (continued):
Sharing a sentence is not in itself a finding about the gene and the disease.
asthma (continued). "Given that asthma is a widespread noninfectious chronic condition marked by type II inflammation, we assessed the levels of Th2-associated cytokines (IL-4, IL-5, and IL-13) in bronchoalveolar lavage (BAL) fluid and serum IgE concentrations." (PMID 41146240, 2025). "These primed DCs induce polarization of type-2 T helper cells (Th2) at regional lymph nodes, and the Th2 cytokines IL-4, IL-5, and IL-13 subsequently promote asthma symptoms by inducing inflammatory cell recruitment, IgE production, excess mucus secretion, and airway smooth muscle cell contraction." (PMID 40517435, 2025). "Patients with asthma display elevated IL-5 levels in both serum and bronchial biopsies." (PMID 41515904, 2025). "This initiative, for instance, notes that for difficult-to-treat severe asthma characterized by eosinophilia or elevated FeNO, the addition of a biologic, such as dupilumab, alongside anti-IL-5 or anti-IgE options, should be considered after a scrutinized specialist assessment." (PMID 40843371, 2025). "Asthma is characterized by a Th2-mediated immune response, which plays a key role in the pathogenesis of allergic airway inflammation by secreting Th2 cytokines such as IL-33, IL-5, and IL-13." (PMID 40422811, 2025). "Reduced IL-5 levels can lead to decreased MC activity, thereby reducing asthma symptoms." (PMID 40933990, 2025). "Approximately 50–80% of patients with asthma present with a T2-high endotype, which may be allergic (IgE-mediated) or eosinophilic (IL-5-mediated), and is driven by cytokines such as interleukin-4 (IL-4), IL-5, and IL-13." (PMID 41405763, 2025). "We performed an in‐depth appraisal of indirect head‐to‐head comparisons of biologics approved for asthma, including anti‐IL5/5Rα (mepolizumab, benralizumab), anti‐IL4Rα (dupilumab), anti‐TSLP (tezepelumab) and anti‐IgE (omalizumab), which was neither a systematic review nor a meta‐analysis." (PMID 40156481, 2025). "Specifically, EPCs derived from asthma patients demonstrate enhanced proliferative capacity and increased integration into endothelial cell tubes, leading to the hypothesis that IL-5 may exert a direct influence on angiogenesis by acting upon EPCs." (PMID 40076985, 2025). "Studies have demonstrated that inflammatory characteristics of asthma may be related to the release of Th2 cytokines (IL-4, IL-5, IL-13 and IL-33) mediated by the regulation of arachidonic acid metabolic pathway." (PMID 40771395, 2025). "Asthma in children is predominantly driven by Th2-type inflammation, characterized by the activation of T-helper 2 (Th2) cells and the overproduction of cytokines such as IL-4, IL-5, and IL-13." (PMID 40003269, 2025). "In addition to the difference observed in TNF‐α between severe and non‐severe asthma, median IL‐5 concentrations were also higher in the severe group (1.7 vs. 0.8 pg/mL; p = 0.010)." (PMID 41159221, 2025). "The peripheral blood eosinophil count is considered to be one of the most reliable, straightforward and methodologically simple biomarkers for classifying asthma subtypes, with serial blood measurements routinely used for monitoring the response to anti-IL-5 therapies." (PMID 41440490, 2025). "Its overexpression was associated with decreased levels of ovalbumin-specific IgE, IL-4, IL-5, and IL-13, contributing to improved asthma outcomes by limiting airway remodeling and autophagy through the downregulation of matrix metalloproteinase (MMP)-16 and autophagy related 7 (ATG7)." (PMID 40871238, 2025). "Cytokine levels of TNF‐α (p = 0.043) and IL‐5 (p = 0.010) differed by asthma severity." (PMID 41159221, 2025). "While Th2-high asthma is driven by cytokines like IL-4, IL-5, and IL-13 and often responds well to corticosteroids and biologics, the pathogenesis and treatment of Th2-low, neutrophilic, or pauci-granulocytic asthma remain less defined and often exhibit steroid resistance." (PMID 41394843, 2025).
asthma (continued). "Consequently, definitive conclusions about the impact of anti-IgE and anti-IL-5 therapy in severe asthma, especially concerning disease complications, life expectancy, or mortality, cannot be drawn." (PMID 40047156, 2025). "Mepolizumab, a blocking monoclonal antibody that targets IL-5, may be helpful in a very small percentage of people with asthma (<0.5%), according to current research." (PMID 39981184, 2025). "However, there is limited and mostly indirect clinical evidence connecting IL-5 modulation to metabolic outcomes, mainly derived from studies on adults with severe asthma treated with anti-IL-5 biologics." (PMID 41007770, 2025). "Increased IL-4, IL-5, IL-13, and IgE production characterize asthma T2 inflammation." (PMID 40486460, 2025). "Biologic therapies for severe asthma include: anti-immunoglobulin (Ig)E (omalizumab); anti-interleukin (IL)-5 (mepolizumab and reslizumab); anti-IL-5 receptor α (IL-5Rα; benralizumab); and anti-IL-4Rα (dupilumab) and anti-thymic stromal lymphopoietin (tezepelumab)." (PMID 41458996, 2025). "Moreover, the addition of metformin to IL-33 reduced the presence of IL-13 and IL-5, thus suggesting the relationship between the long-known biguanide and alarmins in asthma." (PMID 40723867, 2025). "In humans, anti-IL-5 therapies, mainly studied in severe asthma, may affect BMI, but confounding factors like corticosteroid use limit interpretation." (PMID 41007770, 2025). "Vasculitic/ANCA-positive: prioritize B-cell-directed therapy (rituximab ± cyclophosphamide); IL-5 or IL-5Rα blockade may be added for eosinophilia and asthma control." (PMID 41303621, 2025). "As has been observed by others in murine asthma models, we could easily detect IL-5 in the BALF of OVA-sensitized and -challenged animals." (PMID 40725026, 2025). "IL-5 and IL-13 are pivotal in the development of an allergen-sensitized asthma model." (PMID 39820222, 2025). "We observed that only butyrate supplementation significantly alleviated asthma severity, characterized by reduced cell counts (total cells and eosinophils) and type 2 cytokines (IL-4, IL-13, and IL-5) in BALF, as well as total and OVA-specific IgG1/IgE levels in serum." (PMID 40473603, 2025). "Dysregulated Th2 inflammation contributes to the primary pathological mechanism in asthma, driven by Th2 cells that secrete Th2 cytokines (interleukin (IL)-4, IL-5, and IL-13), thereby instigating specific inflammatory cascades and perpetuating an inflammatory response." (PMID 40343297, 2025). "This IL-5 mediated increase in eosinophil numbers might contribute to the augmented asthma-like phenotype in KSRP−/− mice." (PMID 40095032, 2025). "However, blood ILC2s from severe asthma patients treated with mepolizumab, an anti‐IL‐5 biologic, exhibited reduced receptor expression for IL‐7 (i.e., CD127), TSLP, IL‐25 (i.e., IL‐17RB) and PGD2 (i.e., CRTH2)." (PMID 40016948, 2025). "Moreover, MSCs have been shown to reduce levels of IL-5 in patients with asthma, a key cytokine for MC activation." (PMID 40933990, 2025). "For instance, SNPs in IL1RL1 (rs1420101) and IL4RA (rs8832) are linked to enhanced responses to asthma biologics, particularly anti-IL-5 drugs, independent of other clinical factors." (PMID 40004611, 2025). "However, it likely has a limited impact on monitoring the treatment response to anti-IgE and anti-IL-5 therapies in severe asthma patients." (PMID 40047156, 2025). "Research has indicated that altered levels of immune-related miRNAs (such as miR-146a and miR-106b) and inflammatory cytokines (including IL-5 and IL-13) in pediatric asthma may contribute to the progression of the disease." (PMID 40451928, 2025). "This real-world cohort study demonstrated that biological therapy with anti-IL-5 and anti-IL-5R monoclonal antibodies is effective in improving clinical asthma control, quality of life, and lung function in patients with severe eosinophilic asthma who do not respond to conventional treatment." (PMID 40804423, 2025).
asthma (continued). "IL-5 is a potent mediator of eosinophil maturation and has a role in the pathogenesis of asthma." (PMID 40991059, 2025). "Suppressing or upregulating a single molecular route is unlikely to affect asthma because it is caused by a multitude of variables, as demonstrated for IL-4, IL5, and IL-13." (PMID 39981184, 2025). "However, the levels of type-2 cytokines, such as IL-4 (10–25 pg/ml), IL-5 (10–16 pg/ml), and IL-13 (30–70 pg/ml), were enhanced in response to the type-2 high model compared to the type-2 low asthma model (0.5–3 pg/ml, 1–4 pg/ml, and 2–8 pg/ml, respectively)." (PMID 40512736, 2025). "The most correlated targets of the FEO‐03 network on asthma were IL‐13, IL‐4, and IL‐5." (PMID 40777200, 2025). "Our understanding of the complex patterns of inflammation underlying asthma pathogenesis has informed the development of antibody-based biological therapies that target the T2 cytokines, IL-4, IL-5, and IL-13, in adults and in adolescents and children with refractory asthma." (PMID 41440490, 2025). "Interestingly, in patients with asthma, elevated levels of IL-5 and circulating EPCs have been observed." (PMID 40076985, 2025). "Furthermore, levels of OVA‐specific IgE and Th2‐associated cytokines (IL‐4, IL‐5, IL‐13) in BALF were significantly reduced in the sLNP‐OVA/Cel treated group compared to other asthma treatment groups." (PMID 39921498, 2025). "Despite the central role of Th2 cells in producing type 2 cytokines, the field has kept a keen interest in identifying other sources of IL‐4, IL‐5, IL‐9, and IL‐13, which may also be relevant for asthma pathobiology." (PMID 40016948, 2025). "This study will report the effects of anti–IL-5 therapy in both diseases investigated and the respective comorbidity, as well as the consequence of treating milder forms of asthma and CRSwNP with mepolizumab, supporting the emerging evidence on early treatment optimization." (PMID 39554605, 2025). "IL-5 directly activates lung fibroblasts to drive airway remodelling in severe asthma through ECM deposition, MMP/TIMP imbalance, and pro-fibrotic cytokine secretion, positioning it as a dual mediator of inflammation and fibrosis with novel therapeutic potential." (PMID 41188935, 2025). "By targeting specific mediators of this inflammation, such as IgE, IL-5, IL-4, and IL-13, biologics aim to reduce severe asthma exacerbations, improve symptom control, and potentially reduce the need for systemic corticosteroids, thus mitigating their associated risks." (PMID 40486460, 2025). "One patient switched from anti-IL-4 to anti-IL-5 due to uncontrolled asthma." (PMID 40429838, 2025). "The current biologics for severe asthma treatment include omalizumab (anti-IgE), mepolizumab and reslizumab (anti-IL-5), benralizumab (anti-IL-5 receptor), dupilumab (anti-IL-4 receptor α, blocking both the IL-4 and IL-13 pathways), and tezepelumab (anti-TSLP)." (PMID 40364184, 2025). "Given the clinical significance of airway remodeling in asthma, targeting IL-5 or its downstream signaling pathways in fibroblasts may represent a potential therapeutic strategy." (PMID 41188935, 2025). "By promoting eosinophil activity, this pathway increases the production of inflammatory cytokines, such as interleukin-4 (IL-4) and interleukin-5 (IL-5), in conditions such as asthma and chronic rhinosinusitis with nasal polyps (CRSwNP), contributing to chronic inflammation." (PMID 39940325, 2025). "The 2024 GINA report indicated that certain factors may predict a positive response to anti-IL-5 therapy for asthma." (PMID 40303400, 2025). "Anti-interleukin-5 (anti-IL-5) and anti-immunoglobulin E (anti-IgE) agents have already demonstrated significant reductions in asthma exacerbations, while anti-C5a antibodies are being explored in the context of sepsis-related acute respiratory distress syndrome (ARDS) and COVID-19." (PMID 40364149, 2025). "IL-5-targeted agents may support asthma or eosinophilia control but are insufficient for severe vasculitis." (PMID 41303621, 2025).
asthma (continued). "Notably, in the sputum of patients with severe asthma, ILC2s were identified as the predominant cellular source of type 2 cytokines, such as IL-5 and IL-13." (PMID 41409935, 2025). "IL-5 is primarily involved in the development of type 2-high severe asthma." (PMID 40303400, 2025). "However, it has been shown that the number of eosinophils correlates with asthma severity and anti-IL-5 or anti-IL-5 receptor treatment showed beneficial effects in asthma patients." (PMID 40276331, 2025). "Furthermore, the obese asthma model indicates that treatment with GLP-1 receptor agonists results in a cumulative attenuation of IL-5 production from all sources." (PMID 39768911, 2024). "Cytokines like IL-4, IL-5, and IL-13 often propel this immune reaction in asthma." (PMID 39407835, 2024). "In addition, obesity and asthma showed a significant interaction effect on the plasma levels of IL-5, IL-10, IL-17A, IL-33, TNF-α, and leptin." (PMID 39902293, 2024). "In individuals with asthma, exposure to allergens exacerbates this response, leading to heightened airway inflammation and impaired viral clearance due to increased production and secretion of IL-4, IL-5, and IL-13." (PMID 38674586, 2024). "Children with asthma had higher levels of IL-2 (p = 0.005), IL-5 (p < 0.001), IL-13 (p = 0.021), IL-17A (p < 0.001), IL-22 (p < 0.001), IL-33 (p < 0.001), TNF-α (p < 0.001), and lower levels of IL-10 (p = 0.046) and leptin (p < 0.001) compared to those without asthma." (PMID 39902293, 2024). "Indeed, we observed that the IL-5 concentration in the supernatant of splenic cells from IL-5 Tg mice was higher than that of lung cells from the OVA-induced asthma model." (PMID 38540778, 2024). "Thus, we can conclude that in Th2-dependent asthma, eosinophils play the main role of effector cells, and one of the key cytokines is IL-5." (PMID 38921725, 2024). "Anti-IL-5 therapy also improves capsaicin cough sensitivity in patients with severe asthma." (PMID 38785953, 2024). "Moreover, peripheral eosinophils from severe asthma patients showed greater EET formation in response to IL-5 or lipopolysaccharide (LPS) stimulation." (PMID 38495619, 2024). "IL-5 has been identified as a therapeutic target for eosinophilic diseases and several monoclonal antibodies have been approved for clinical use in the treatment of severe asthma, for example, mepolizumab and reslizumab targeting IL-5, and benralizumab targeting the IL-5 receptor." (PMID 39175819, 2024). "Medical treatments can thus be designed to target IL-5 and IL-9 to prevent asthma exacerbations." (PMID 39175819, 2024). "The results of our MR analysis do not support the genetic prediction that IL-5 increases the risk of asthma." (PMID 39175819, 2024). "In vitro studies of epithelial and stromal cells frequently simulate T2-high immune environments with addition of the classical Th2 cytokines IL-4, IL-5, and IL-13, but fail to recapitulate many epithelial genes that are differentially expressed in T2-high asthma or nasal polyps in vivo." (PMID 38444858, 2024). "The degree of the disease’s severity is associated with the abundance of type 2 innate lymphoid cells (ILC2s); patients with severe asthma exhibit higher counts of IL-5 and IL-13 secreting ILC2s in their sputum compared to those with milder forms of the condition." (PMID 38680486, 2024). "These immunological markers may correspond to pathophysiological characteristics of asthma: periostin, IgE, IL-5, and IL-33 for T2 asthma; IL-6, IL-8, IL-17A, and IL-33 for non-T2 asthma." (PMID 38256660, 2024). "Biologic therapies targeting key inflammatory pathways involved in viral-induced exacerbations, such as interleukin (IL)-4, IL-5, and IL-13 in asthma, and tumor necrosis factor-alpha (TNF-α) and IL-1 in COPD, show potential for modulating airway inflammation and reducing respiratory symptoms." (PMID 39458339, 2024).
asthma (continued). "In the present study, we evaluated the expression levels of activation‐ and function‐related genes in interleukin (IL)‐5‐ or IL‐17‐activated eosinophils derived from patients receiving Global Initiative for Asthma (GINA) 4 or 5 treatment and those receiving GINA 3 treatment." (PMID 39575691, 2024). "The immunomodulatory property of E. granulosus infection and its cyst fluid proteins on human immune system have been demonstrated previously in the treatment of ovalbumin (OVA)-induced asthma in mice by increasing IL-10 and Tregs and down-regulating IL-5, IL-17." (PMID 39548530, 2024). "The probability of uncontrolled asthma when treated with anti-IL5/5R therapy was reduced from 0.42 (95% CI: 0.36, 0.48) at BEC of 50 cells/μL to 0.24 (95% CI: 0.19, 0.30) at BEC 1000 cells/μL, but remained relatively constant in the anti-IgE group, ranging from 0.35 to 0.32 over the same BEC range." (PMID 38711495, 2024). "IL-5 levels increase when eosinophilic counts also increase during asthma development." (PMID 39175819, 2024). "Mepolizumab, the first widely available anti-interleukin 5 biologic, targets eosinophilic inflammation and has been shown in clinical trials to reduce exacerbations, oral corticosteroid dependence, and healthcare utilization in patients with severe asthma." (PMID 38311747, 2024). "Furthermore, we summarized the current knowledge on therapeutic applications of IL-5 inhibition in eosinophilic asthma difficult-to-treat, and severe asthma." (PMID 39062104, 2024). "These therapeutic effects of both biologics are of particular importance in the case of steroid-requiring asthma, as controlled studies have shown that the use of anti-IL-5 or anti-IL-5Rα antibodies enables a reduction or complete discontinuation of systemic corticosteroids." (PMID 39600395, 2024). "The identification of eosinophilic pathways and the IL-5 axis, integrin signaling, and exosome release offers new targets for developing novel treatments aimed at reducing airway inflammation and remodeling by improving outcomes in patients with severe asthma." (PMID 39518415, 2024). "In addition, several studies primarily evaluating asthma showed that patients obtained significant improvements in upper airway outcomes with all three options blocking IL-5." (PMID 38367543, 2024). "Furthermore, in the CALIMA study, it was concluded that the association of T2 asthma with NP was a predictor of response to anti-IL-5 antibodies in asthma." (PMID 39064286, 2024). "Furthermore, hesperidin as flavonoid aglycone has a distinctive role in the treatment of asthma via modulation of certain biomarkers such as reactive oxygen species and IL-5 production." (PMID 37950769, 2024). "Indeed, anti-IL-5 treatment, such as with an anti-IL-5 antibody (Ab) or an anti-IL-5R Ab, reduces the blood eosinophil count and asthma exacerbation frequency in patients with severe asthma with an increased blood eosinophil count." (PMID 38785953, 2024). "Moreover, the level of Th2 cytokines (IL‐4 and IL‐5) in the mice with acute asthma exacerbation increased more obviously which was blocked by GW administration." (PMID 38938285, 2024). "When it comes to asthma pathogenesis, IL-5 is known to have a pivotal role." (PMID 39062104, 2024). "In patients with concomitant high eosinophil levels whose asthma remains uncontrolled, switching to an anti-eosinophilic treatment (i.e., anti-IL5/5R) might be a good option." (PMID 38711495, 2024). "In this review, we discuss the currently limited literature on the role of mitochondria in eosinophil function and how it is regulated by asthma-relevant cytokines, including interleukin (IL)-5 and granulocyte-macrophage colony-stimulating factor (GM-CSF), as well as by corticosteroid drugs." (PMID 38495619, 2024). "GM-CSF and IL-5 are clinically important in the pathophysiology of allergies and asthma." (PMID 38339007, 2024).